AFP (alpha fetoprotein)
Diseases named in the same sentence as AFP in open-access papers (continued):
Sharing a sentence is not in itself a finding about the gene and the disease.
Cirrhosis (continued). "CHD patients with cirrhosis had higher levels of AFP (p = 0.012), AST (p = 0.001), ALT (p < 0.001), and lower levels of PLT (p < 0.001) when compared to CHB patients with cirrhosis." (PMID 38138039, 2023). "In this study, we compared the diagnostic performances of serum AFP with APRI and FIB-4 in predicting significant fibrosis, advanced fibrosis, and cirrhosis in HBeAg-positive CHB patients." (PMID 37241155, 2023). "In our study, AFP levels in the HCC group were significantly higher than in the cirrhosis group (<0.0001)." (PMID 37046471, 2023). "For the GSE14520 cohort, nomograms were constructed using tumor size, cirrhosis, α-fetoprotein (AFP), Barcelona Clinic Liver Cancer (BCLC) stage, APOL3 and APOL6 expressions for OS." (PMID 38017264, 2023). "Several studies have demonstrated that elevated serum AFP levels are highly specific for the diagnosis of advanced fibrosis and cirrhosis in patients with chronic Hepatitis C (CHC)." (PMID 37241155, 2023). "Currently, the major clinicopathological variables that are utilized to predict the prognosis of HCC include age, sex, alpha-fetoprotein (AFP) levels, cirrhosis, and tumor stage." (PMID 38021150, 2023). "To further investigate the association between different genotypes and OS in the 866 cases, we performed a stratified analysis using covariates such as age, sex, smoking, drinking, AFP, cirrhosis, embolus, and BCLC stage as stratification factors." (PMID 38260847, 2023). "The serum AFP level is an independent risk factor of HCC, but its prognostic role is limited in patients with well-compensated cirrhosis with a single small HCC who undergo treatment with curative intent." (PMID 37374267, 2023). "For OS, univariate analysis showed that cirrhosis (P = 0.020), AFP level (P = 0.012), vascular invasion (P < 0.001), AJCC stage (P = 0.007), and a high AGR2 level (P = 0.018) were significant predictors of worse OS." (PMID 36899352, 2023). "Additional risk factors include male gender, advanced age (greater than 65 years), the presence of cirrhosis, chronic alcohol abuse, genotype 3, diabetes, metabolic syndrome, low albumin/platelet levels, and elevated alpha-fetoprotein (AFP) levels." (PMID 38201624, 2023). "These patients had a poorer liver function and a higher prevalence of severe fibrosis/cirrhosis compared to those with normal AFP levels." (PMID 37241155, 2023). "In conclusion, serum AFP is a useful biomarker for identifying significant fibrosis, advanced fibrosis, and cirrhosis in HBeAg-positive CHB patients." (PMID 37241155, 2023). "Univariate analysis showed that cirrhosis (P = 0.022), AFP level (P = 0.033), vascular invasion (P = 0.003), AJCC stage (P = 0.003), and a high AGR2 level (P = 0.047) were significant predictors of worse RFS." (PMID 36899352, 2023). "Probably the emerging role of PIVKA II is in patients with previous hepatic diseases (hepatitis, cirrhosis) where AFP limitations are well-known." (PMID 36899960, 2023). "Independent factors associated with elevated AFP levels included female gender, increased tumor size, multiple tumors, BCLC stages B–D, cirrhosis, total bilirubin > 1.4 mg/dL, and viral etiology." (PMID 36831565, 2023). "This means that the positive detection of anti-CNN2 antibody in the serum cannot be attributed to factors such as age, gender, AFP value, pathological grade, presence of cirrhosis, ALT value, AST value, HBsAg, and tumor size." (PMID 37373013, 2023). "The multivariate analysis showed that gender, age, the presence of cirrhosis, DM, hypertension, dyslipidemia, CCI, receipt of curative HCC treatment, and the frequency of AFP testing were independent risk factors for overall survival in patients with HCC." (PMID 38201578, 2023). "For OS, univariate analysis showed that cirrhosis (P = 0.023), AFP level (P = 0.011), tumor size (P = 0.001), CLIP score (P < 0.001), BCLC stage (P < 0.001), AJCC stage (P < 0.001), and a high AGR2 level (P = 0.002) were significant predictors of worse OS." (PMID 36899352, 2023).
Cirrhosis (continued). "Univariate proportional hazards analyses suggested that CLIP staging, BCLC staging, multinodular, tumor size, serum AFP level, TNM staging, cirrhosis, and the high-risk score were risk factors for prognosis." (PMID 37301543, 2023). "gender, ALT level, AST level, platelet count, lymphocyte count, neutrophils count, HBV infection, tumor size, tumor number, BCLC stage, portal invasion, extrahepatic expand, cirrhosis, ascites, alpha-fetoprotein (AFP) level, Child-Pugh class, ECOG." (PMID 38074659, 2023). "The study population comprised patients with cirrhosis who underwent biannual surveillance with liver imaging and AFP." (PMID 37708457, 2023). "Another study showed that circ_0070396 was highly expressed in EVs of HCC and outperformed AFP in distinguishing HCC patients from chronic hepatitis B/cirrhosis or healthy donors." (PMID 37006626, 2023). "As expected, AFP and PVIKA-II exhibited limited discriminatory ability when tested at established cutoffs for distinguishing between HCC and cirrhosis (AFP <20 ng/mL, AUC 0.72; PIVKA-II 40 mAU/ml, AUC 0.68)." (PMID 37708457, 2023). "The AFP levels increase in patients with active hepatitis or cirrhosis, while low levels of AFP are correlated with a good response to nucleos(t)ide analogs in chronic hepatitis B or to direct-acting antivirals (DAA) treatment for chronic hepatitis C." (PMID 35626300, 2022). "Given that the main cause of liver cancer in Uzbekistan is expected to be hepatitis virus and related cirrhosis, nationwide screening using sonography and alpha-fetoprotein testing is recommended." (PMID 36142000, 2022). "Studies have pointed out that the level of circSMARCA5 can effectively distinguish patients with liver cancer hepatitis and liver fibrosis rom healthy controls, and it is also meaningful in patients with hepatitis and cirrhosis with AFP < 200 ng/ml." (PMID 35712125, 2022). "Screening for HCC is advised in patients with cirrhosis with imaging (typically ultrasound) as well as serum AFP." (PMID 36135076, 2022). "The tumor size, serum alpha-fetoprotein, presence of cirrhosis, microvascular invasion and administration of antiviral therapies have been identified as prognostic factors for recurrence after resection." (PMID 35208582, 2022). "The results showed that the HCC patients in the cirrhosis group were more likely to be younger and have an elevated AFP level; decreased WBC, NEU, and PLT concentrations; poor coagulation function; smaller tumour size; and multiple tumours." (PMID 36100893, 2022). "While validating the Y3PSVR thresholds of LS and AFP, the results of Kaplan–Meier analyses were both significant in the group with cirrhosis at baseline (n = 63) (P=0.042) and in that without cirrhosis at the baseline (n = 457) (P=0.006), respectively." (PMID 35837486, 2022). "Further analyses to assess the diagnostic performance of the ASAP score, the GALAD score, AFP, PIVKA-II, and AFP-L3% to detect HCV-HCC among patients with HCV-cirrhosis (HCC, n = 147; control group, n = 139) were then performed." (PMID 36263214, 2022). "This study aims to compare multiple biomarkers (including AFP, the Doylestown algorithm, and aMAP score) in Chinese patients with cirrhosis and investigate the clinical utility of the Doylestown algorithm and aMAP score." (PMID 35218083, 2022). "The reported risk factors for tumor recurrence are the presence of satellite nodules, high baseline AFP levels, poor liver function, and the presence of cirrhosis." (PMID 36366525, 2022). "All patients with AFP over 500 ng/ml were cirrhotic, with a predominance of decompensated cirrhosis and multinodular HCC pattern." (PMID 35497085, 2022). "We identified male sex, cirrhosis, AFP ≥ 100 μg/L, AST ≥ 70 u/dL, total bilirubin (>2.0 mg/dL), INR > 1.7, SII > 610 × 109 cells/L, advanced tumor stage TNM, and MELD score as risk factors for poor outcomes." (PMID 35735455, 2022).
Cirrhosis (continued). "High GH levels were associated with advanced disease and poor clinical outcome including more frequent cirrhosis, poorly differentiated tumors, multi-nodularity, vascular invasion, higher α-fetoprotein (AFP) levels, and advanced clinicopathological staging." (PMID 36276070, 2022). "This score includes age, gender, cirrhosis, and levels of AFP (between 4.1 and 20 microg/mL vs. >20 microg/mL)." (PMID 35008926, 2022). "Mean AFP among patients with decompensated cirrhosis was 660 ng/ml and the mean HCC size for this category was 5.8 cm, with maximum tumour diameter ranging between 3.3 and 8.2 cm." (PMID 35497085, 2022). "Regarding AFP, participants with HCC had also a higher mean of AFP of 249.8±6.1 ng /ml, followed by participants with cirrhosis 82.3±10.7 ng /ml, and finally participants with CH 58.5±26.3 ng /ml (P<0.0001)." (PMID 36590993, 2022). "Gender (P = 0.021), cirrhosis (P = 0.036), and BCLC stage (P < 0.001) were associated with the RFS of HBV-related HCC, and the AFP level (P = 0.049), BCLC stage (P < 0.001), cirrhosis (P = 0.041), and tumor size (P = 0.002) were independent predictors for OS." (PMID 35311629, 2022). "Patients with HCC and compensated cirrhosis had mostly AFP levels between 100 and 300 ng/ml, with a mean value of 278 ng/ml." (PMID 35497085, 2022). "This case illustrated that the non-invasive diagnostic criteria for liver cancer should be considered carefully when discovering a space-occupying liver lesion in a patient with cirrhosis and an elevated AFP level." (PMID 36457572, 2022). "The association between risk score and clinical characteristics including age, gender, grade, stage, and vascular invasion and the value of AFP, cirrhosis, HBV infection status, and tumor status were evaluated." (PMID 36003068, 2022). "The impact of cirrhosis etiology of serum AFP levels is well established and generally higher levels are seen in patients with HCV." (PMID 36230823, 2022). "Diagnostic performances of the ASAP score, the GALAD score, AFP, PIVKA-II, and AFP-L3% for detecting any stage HCV-HCC in the overall group and the cirrhosis subgroup." (PMID 36263214, 2022). "Age, alcoholism, DM, viral hepatitis and high levels of GGT, AFP and creatinine are also confirmed as predictors of both diseases, while smoking, alcoholism and DM are predictors of isolated cirrhosis." (PMID 35919232, 2022). "Next, through analysis of the ANKFN1 IHC scores in HCC tissues, we observed that high HCC expression correlated with cirrhosis and higher AFP levels." (PMID 35725908, 2022). "Additional analysis was performed to analyze the relationships between TMB/neoantigen load and sex, age, microvascular invasion (MVI), hepatitis B surface antigen (HBSAg), smoking, alcohol, cirrhosis, serum alpha‐fetoprotein (AFP) status." (PMID 35665491, 2022). "Diagnostic performances of the ASAP and the GALAD score for detecting AFP-negative HCV-HCC (AFP<20 ng/ml) in the overall group and the cirrhosis subgroup." (PMID 36263214, 2022). "It includes male gender, alcohol use, cirrhosis, age, diabetes, AFP and platelet count to divide patients in three categories with an annual incidence rate of 0.09, 0.9, and 5.8% respectively." (PMID 35008926, 2022). "AFP expression levels were also found to be upregulated in patients with benign liver diseases, such as cirrhosis and hepatitis." (PMID 36584078, 2022). "Patients with high levels of RI (RIhigh, RI > 136.17) were more likely to have higher AFP level and cirrhosis stage as well as CYP2E1 activity, indicating that the established method has substantial clinical value." (PMID 35314790, 2022). "For RFS, univariate analysis showed that significant prognostic factors included preoperative AFP level, cirrhosis, tumor number, satellite lesions, maximal diameter, histological grade and PVTT." (PMID 36203429, 2022).
Cirrhosis (continued). "A recent Korean study revealed that cirrhosis at baseline, platelet count and AFP at 12 months of NA treatment were the optimal predictive factors for HCC in CHB patients receiving entecavir or TDF treatment." (PMID 36291847, 2022). "Chinese guideline for stratified screening and surveillance of primary liver cancer (2020 Edition) recommends abdominal ultrasonography combined with serum a‐fetoprotein (AFP) every 6 months as a surveillance program for HCC in patients with cirrhosis." (PMID 35218083, 2022). "Further analysis of the AUC curve confirmed that MALAT1 expression was helpful in the differentiation of patients with cirrhosis, vascular invasion, capsule infiltration, and AFP positivity." (PMID 36685103, 2022). "AFP mRNA levels in cirrhosis and HCC patients were similar in the two datasets, whereas CCT7 levels were significantly higher in HCC patients than in cirrhosis patients." (PMID 35073517, 2022). "Of note, AFP as a consensus risk factor, elevated value not only indicates HCC development but activate hepatitis or cirrhosis." (PMID 35761201, 2022). "The multivariate Cox regression model proved that TRGs signature was an independent risk factor adjusting for clinical characteristics such as tumor size, nodule number, cirrhosis status, and alpha-fetoprotein (AFP) level." (PMID 36341373, 2022). "We subsequently found that low STAG3 expression was correlated with cirrhosis, higher AFP levels, larger tumor size and lower pathological stage." (PMID 35941537, 2022). "Some studies have shown that PIVKA-II was superior to other markers (alpha-fetoprotein [AFP] and lens culinaris agglutinin-reactive fraction of AFP [AFP-L3%]) in differentiating primary liver cancer from cirrhosis." (PMID 35271670, 2022). "Median AFP values were significantly different between patients with cirrhosis and those with HCC (p < 0.001)." (PMID 33799723, 2021). "XIST had a significant discriminatory power to differentiate early-stage HCC group with healthy, CHB, and cirrhosis, compared to AFP." (PMID 33477833, 2021). "Most HCCs develop in the setting of cirrhosis; however, current early detection strategies, using abdominal ultrasound and alpha-fetoprotein (AFP), have inadequate sensitivity and specificity for early detection." (PMID 34436504, 2021). "The study also showed that a panel consisting of miR-122-5p, miR-486-5p and miR-142-3p was capable of distinguishing HCC from cirrhosis while outperforming the only current biomarker alpha-fetoprotein (AFP)." (PMID 34510227, 2021). "Higher serum AFP levels have been reported to correlate significantly with advanced liver fibrosis and cirrhosis." (PMID 33289529, 2021). "Further investigations, including liver imaging and biochemistry, revealed the presence of Child-A cirrhosis with very high AFP levels (29,953 ng/mL)." (PMID 33922938, 2021). "This study demonstrated that SBRT is an effective treatment for HCC and that clinical T stage, presence of cirrhosis, age, AFP levels, and haemoglobin levels were independent prognostic factors for OS." (PMID 34126955, 2021). "When cHCC-CC and CC groups were compared, significant differences were noted regarding diabetes mellitus, alcohol use, cirrhosis, AFP level ≥ 200 ng/mL, operative margin > 1 cm, major hepatectomy, microvascular invasion, and macrovascular invasion." (PMID 33413162, 2021). "Treatment type, CP class A, cirrhosis, ascites, serum total bilirubin, serum albumin, ALBI grade, and serum AFP were strongly associated with OS in the univariate analysis." (PMID 34749663, 2021). "Thus, monitoring HCC risk in CHB or cirrhosis patients by PIVKA‐II may be more specific than AFP." (PMID 34590755, 2021). "The combination of AFP with fucosylated sialylated N-glycopeptides showed better results, because both the analytes increased their abundance from cirrhosis to HCC." (PMID 34436504, 2021).
Cirrhosis (continued). "The laboratory data showed statistically significantly higher values of ALT, AST, INR, S. bilirubin and AFP in the HCC group as compared to the cirrhosis group." (PMID 34181338, 2021). "With active HCC surveillance in patients with cirrhosis, AFP levels at diagnosis continue to trend lower, with many recent studies reporting interquartile ranges of AFP < 20 ng/mL." (PMID 34638251, 2021). "Then, we recorded the clinicopathological characteristics of 65 patients with HCC, including age, gender, tumor size, tumor node metastasis stage, tumor multifocality, venous invasion, HBsAg infection, alpha fetoprotein indicators, and cirrhosis." (PMID 34659578, 2021). "The chi-square test showed that the prognostic signature exhibited a close relationship with histology grade, vascular tumor cell type, AFP, new tumor event after initial treatment, main tumor size, cirrhosis, TNM stage, BCLC stage, and CLIP score (p < 0.05)." (PMID 34869350, 2021). "Nevertheless, test for AFP improves performance of diagnosis and served as a valuable surveillance test for HCC associated with HCV-caused cirrhosis with normal level of alanine aminotransferase (ALT)." (PMID 33562077, 2021). "The association between risk score and clinical characteristics including age, gender, grade, stage, vascular invasion, value of AFP, cirrhosis, and tumor status were evaluated." (PMID 34627241, 2021). "The combination of hsa_circ_0028861 and AFP exhibited better diagnostic ability (AUC = 0.86 for discriminating HCC from chronic HBV and cirrhosis)." (PMID 34367259, 2021). "Next, we constructed a nomogram for OS based on the following clinical features: BCLC stage, cirrhosis, serum AFP level, tumor size and SOX4 expression." (PMID 33995626, 2021). "Prognostic factors for HCC have been shown to include tumour size, tumour type, tumour stage, presence of cirrhosis, Child-Pugh class, AFP level, and serological indicators of liver function, consistent with our study findings." (PMID 34126955, 2021). "Several factors are prognostic for recurrence and/or survival after resection in HCC, including tumor size and differentiation, serum α-fetoprotein (AFP), microvascular invasion, cirrhosis, surgical margin and metabolic syndrome." (PMID 34199695, 2021). "Many factors are known to affect the risk of recurrence in HCC, including tumor size, alpha-fetoprotein (AFP), microvascular invasion, cirrhosis, resection margin, and the viral replication status of HBV and HCV." (PMID 34945733, 2021). "The analysis of their baseline characteristics revealed significant risk factors associated with 121 cases of HCV infection and 75 cases of HCV-HCC, which included age (p = 0.0001), AFP (p = 0.0001), cirrhosis (p = 0.002), and platelet number (p < 0.001)." (PMID 34680563, 2021). "These factors included age, gender, platelet counts, serum TB, AST, ALT, albumin, AFP level, presence of cirrhosis, tumor size and BCLC stage." (PMID 34045534, 2021). "The mRNA expression of ACE2 was related to the age, alpha-fetoprotein levels and cirrhosis of HCC patients, and it was identified as a protected factor for HCC patients via Kaplan–Meier survival, Cox regression analyses." (PMID 34369278, 2021). "The results demonstrated that sex, age, ECOG performance status score, presence of cirrhosis, clinical T stage, Child-Pugh class, alpha-fetoprotein (AFP) levels, albumin (ALB) levels, and haemoglobin (HGB) levels were significantly related to the OS rate." (PMID 34126955, 2021). "Under the current guidelines, monitoring for HCC with liver imaging and blood AFP (alpha-fetoprotein) biomarker levels should be performed twice a year indefinitely post-SVR in patients with HCV cirrhosis." (PMID 34680227, 2021). "Otherwise, some important clinical information of 24 patients, including PT, DBIL, TBIL, AST, ALT, tumor number, embolus, differentiation, capsule, AFP, cirrhosis, gender, and age, was labeled." (PMID 33414412, 2021).